TXNIP (thioredoxin interacting protein)
Diseases named in the same sentence as TXNIP in open-access papers (continued):
Sharing a sentence is not in itself a finding about the gene and the disease.
breast carcinoma (59 papers, 2007 to 2025). "This is the first demonstration that TXNIP positively affects IL-24 expression in breast cancer cells, although the mechanism underlying this positive correlation is unclear." (PMID 40175348, 2025). "To elucidate the mechanisms underlying TXNIP’s antitumor effects in breast cancer cells, we conducted co-immunoprecipitation and proteomic analyses that revealed calpastatin (CAST) as a novel TXNIP-interacting protein in MDA-MB-231 and HCC-1954 cells." (PMID 40175348, 2025). "A prognostic model was constructed using these three genes, and the results showed that high expression of SLC2A1 is associated with poor prognosis in breast cancer patients, while low expression of TXNIP and ATF3 is associated with poor prognosis." (PMID 38244591, 2024). "Targeted therapies in breast cancer such as trastuzumab, cetuximab, and lapatinib, which block the Her-1/2 pathway, can cause G1 cell cycle arrest and also highly increase TXNIP expression." (PMID 37794178, 2023). "TXNRD1 and thioredoxin interacting protein (TXNIP) were associated with poor breast cancer prognosis, and ERBB2 was suggested to play a role in altering their redox control pathway." (PMID 35158912, 2022). "Altogether, the multifaceted metabolic reprogramming induced by DASA-58 in breast cancer cells increases their susceptibility to other therapeutics suggesting the suitability of the intracellular glucose sensor TXNIP as a marker of PK activity." (PMID 33482908, 2021). "A recent study on the association of TXNIP expression and metastasis-free survival of breast cancer patients found that TXNIP was associated with better prognosis." (PMID 25605021, 2015). "Here, we investigated TXNIP expression in early stage breast cancer patients and its association with OS." (PMID 25605021, 2015). "We found that TXNIP expression was associated with better overall survival (OS) in these 150 breast cancer patients and that TXNIP and Her-2 expression status were significantly inversely correlated (r=-0.334, P<0.001)." (PMID 25605021, 2015). "In human breast cancer, high TXNIP levels are associated with longer metastasis-free intervals and better prognosis than those with low TXNIP expression." (PMID 24645981, 2014). "We have shown that the shift to lactate metabolism in excess of glucose is associated with increased levels of TXNIP protein that increases ROS levels through inhibition of TRX activity in breast cancer derived cells MDA-MB-231." (PMID 21910912, 2011). "TXNRD1 and TXNIP are associated with prognosis in breast cancer, and ERBB2 seems to be one of the factors shifting balances of both factors of the redox control system in a prognostic unfavorable manner." (PMID 20584310, 2010). "In the present study we observed that high expression of TXNRD1 and low expression of TXNIP are associated with worse prognosis in breast cancer." (PMID 20584310, 2010). "High expression of TXN and TXNRD1 with low expression of TXNIP was associated with dysfunctional T cell phenotype and shorter survival of the breast carcinoma cohort and colorectal carcinoma cohort, in accordance with the abnormal expression status of the Trx system in BRCA and COAD." (PMID 39744566, 2025). "Reintroducing TXNIP into TXNIP-deficient HCC-1954 breast cancer cells decreased cell proliferation and migration while boosting the generation of reactive oxygen species, alongside reductions in mitochondrial respiration, mitochondrial membrane potential, and glycolysis." (PMID 40175348, 2025). "Additionally, in ER+ breast cancer, the levels of TXNIP expression in tumor cells are associated with different metabolic subtypes." (PMID 37794178, 2023). "Due to the strong correlation between elevated TXNIP mRNA expression and an improved prognosis, it has been suggested that TXNIP may be a suitable diagnostic biomarker for breast cancer in humans." (PMID 36366411, 2022).
breast carcinoma (continued). "Since elevated levels of Trx-1 are associated with tumor progression the increase of TXNIP protein was associated with a higher overall survival of patients with mammary carcinomas suggesting that TXNIP could inhibit tumor progression." (PMID 33407762, 2021). "Moreover, high TXNIP and p27 expression were associated with better OS in human breast cancer patients." (PMID 25605021, 2015). "Our findings revealed novel cross-organ pathogenic communication between breast cancer and the heart through the exosomal miR-216a-5p-mediated ITCH/TXNIP/NLRP3 pathway, which drives cardiomyocyte pyroptosis." (PMID 40360476, 2025). "In conclusion, our study demonstrates TXNIP’s multifaceted role in breast cancer, influencing redox balance, mitochondrial function, and cell fate." (PMID 40175348, 2025). "As an example, the oncogene c-Myc is a known inhibitor of TXNIP in multiple cancers, TXNIPlow/Mychigh induces metabolic reprogramming and is a marker of poor prognosis in breast cancer, and therapy resistance." (PMID 41213907, 2025). "According to The Cancer Genome Atlas, TXNIP mRNA expression is frequently downregulated in human breast cancer (BC), lung squamous cell carcinoma, colon adenocarcinoma, and many other cancers relative to the corresponding normal tissues." (PMID 40175348, 2025). "For example, exosomal miRNA-146a derived from breast cancer cells induces the activation of CAFs by downregulating TXNIP to active Wnt/β-catenin axis, which promotes breast cancer progression." (PMID 40490663, 2025). "These insights highlight the potential of targeting the TXNIP-IL-24 pathway as a therapeutic strategy in breast cancer, opening up a potential avenue for future research and treatment development." (PMID 40175348, 2025). "In this study, we have demonstrated TXNIP’s anticancer effects in MDA-MB-231 (high endogenous TXNIP) and HCC-1954 (low endogenous TXNIP) breast cancer cells." (PMID 40175348, 2025). "In breast cancer, TXNIP knockdown increased Ki-67 expression (a marker of cell proliferation) and decreased p27 (a cell cycle regulatory protein), leading to enhanced breast cancer cell growth in vitro and in vivo." (PMID 40182050, 2025). "It is of interest that MDA-MB-231 and MCF7 cells, though both of ductal breast cancer origin, show differential upregulation of TXNIP by Dpep." (PMID 38920655, 2024). "TXNIP has great potential as a therapeutic target for breast cancer, as studies have shown that it is a good biomarker and prognostic evaluation gene for breast cancer." (PMID 38244591, 2024). "In summary, the three key ferroptosis-related genes (TXNIP, SLC2A1, ATF3) are closely associated with the development and prognosis of breast cancer." (PMID 38244591, 2024). "Thioredoxin-interacting protein (TXNIP) is a crucial thioredoxin-binding protein that isrecognized as a tumor suppressor in diverse malignancies, such as breast cancer, lungcancer, hepatocellular carcinoma, and thyroid cancer." (PMID 38229544, 2024). "Intriguingly, TXNIP and RERG have also been reported to be linked to breast cancer suppression associated with better prognosis." (PMID 38282415, 2024). "Downregulation of SLC2A1 expression promoted ferroptosis and suppressed tumor cell growth in breast cancer cells (P < 0.01), while overexpression of TXNIP or ATF3 had the same effect (P < 0.01)." (PMID 38244591, 2024). "This study identified three key ferroptosis-related genes (TXNIP, SLC2A1, ATF3) associated with breast cancer by integrating bioinformatics analysis and multiple machine learning algorithms, and preliminarily validated their roles through cell experiments." (PMID 38244591, 2024). "In breast cancer, TXNIP can suppress cellproliferation via metabolic reprogramming and attenuate cell invasion and migration throughthe TXNIP-HIF1α-TWIST signaling pathway." (PMID 38229544, 2024).
breast carcinoma (continued). "Breast cancer-derived exosomes induce CAFs to activate the Wnt pathway through the miR-146a–TXNIP axis, thereby enhancing invasion and metastasis of breast cancer cells." (PMID 37978384, 2023). "The CISD2 (NAF-1, nutrient-deprivation autophagy factor-1) protein is reported to regulate TXNIP expression through a process that involves the perturbation of mitochondrial labile iron, mitochondrial ROS and triggered ferroptosis in breast cancer cells." (PMID 37794178, 2023). "For instance, in breast cancer, c-Myc has been exhibited to antagonise TXNIP expression in MondoA-dependent pathway." (PMID 37794178, 2023). "Many studies have shown that the expression of TXNIP is at a low level in different types of cancer (such as liver cancer, breast cancer, and lung cancer), and the overexpression of TXNIP inhibits the proliferation of cancer cells." (PMID 35450411, 2022). "TXNIP is considered to be a potential tumor suppressor gene in multiple tumors, including breast cancer, hepatocellular carcinoma, non-small-cell lung cancer, and renal cell carcinoma." (PMID 36428626, 2022). "miR-146a targets thioredoxin-interacting protein (TXNIP) to promote breast cancer cell fibrosis and exacerbate cell metastasis in the EMT process." (PMID 35805066, 2022). "TXNIP modifies the metabolic reprogramming in a breast cancer cell by influencing invasion, migration, and suppressing metastasis of cancer cells through the TXNIP-HIF1α-TWIST signaling axis." (PMID 36366411, 2022). "During breast cancer progression, miR-373 quenched ROS levels by downregulating the ROS inducer thioredoxin-interacting protein (TXNIP), stimulating HIF-1α and TWIST expression." (PMID 35081965, 2022). "Results of the TXNIP proteomic expression profile analysis showed absolutely lower expression of TXNIP total protein in the primary tissues of breast cancer, colon cancer, ovarian cancer, LUAD and UCEC (all P < 0.001) than in normal tissues." (PMID 35843949, 2022). "When compared to normal tissues, TXNIP expression was markedly downregulated in animal epithelium tumors and human breast cancer tissues." (PMID 36366411, 2022). "We also analyzed the correlation of TXNIP expression and the selected clinicopathological factors in liver, lung, and breast cancer, and finally observed distinct conclusions concerning these tumors." (PMID 35843949, 2022). "Previous studies have shown that TXNIP exerts a tumor suppressor effect on the occurrence and development of liver cancer, breast cancer, and lung cancer and plays a key role in mediating apoptosis and tumor cell cycle arrest." (PMID 35414060, 2022). "Increasing evidence demonstrated that TXNIP was a tumor suppressor and was shown a low expression in liver cancer, breast cancer, and lung cancer." (PMID 34277424, 2021). "TXNIP gene knockout can promote the proliferation of breast cancer cells, which is accompanied by decreased p27 expression and increased glucose transporter type 1 (GLUT1) levels." (PMID 33194655, 2020). "TXNIP is known to inhibit the proliferation of breast cancer cells by affecting metabolic reprogramming and can affect the invasion and migration of breast cancer cells through the TXNIP-HIF1α-TWIST signaling axis." (PMID 33194655, 2020). "Apart from Trx, high TxNIP expression was also a prognostic factor for better overall survival in this cohort, which is consistent with a study conducted in locally advanced breast cancer patients." (PMID 32418115, 2020). "While our current experiments focus on TXNIP induction by RocA, our previous work demonstrated that a slightly acidic pH of ~ 6.7 drives a gene signature that correlates with good clinical prognosis in breast cancer, and TXNIP is a component of that signature." (PMID 33292639, 2020).
breast carcinoma (continued). "In contrast, TXNIP expression positively correlated with an acidosis gene-signature in breast cancer." (PMID 30717828, 2019). "Further, an acidosis-dependent gene signature, of which TXNIP is a member correlates with better clinical outcomes in breast cancer." (PMID 30717828, 2019). "Using flow cytometry to explore the role of TXNIP in the cell cycle control and cell proliferation in breast cancer, we found that TXNIP overexpression enhanced G1 cell cycle arrest and induced apoptosis both in BT474 and SK-BR-3 cell lines." (PMID 25605021, 2015). "Based on immunohistochemical (IHC) staining of 98 locally advanced primary breast cancer patients, TXNIP was found to be an independent prognostic factor for distant metastasis-free survival." (PMID 25605021, 2015). "Clinically, miR-373 is negatively associated with TXNIP and positively associated with HIF1α and TWIST, and activation of the miR-373-TXNIP-HIF1α-TWIST signaling axis is correlated with a worse outcome in patients with breast cancer." (PMID 26196741, 2015). "Previous studies have indicated that Her-2 induction causes a strong decrease in thioredoxin interaction protein (TXNIP) in breast cancer cells." (PMID 25605021, 2015). "TXNIP and p27 expressions were decreased in breast cancer tissue compared with NCTs (P =0.003, P <0.001, respectively)." (PMID 25605021, 2015). "When treated with the anti-Her-1 monoclonal antibody cetuximab, the anti-Her-2 monoclonal antibody trastuzumab or the dual Her-1/2 inhibitor lapatinib, TXNIP mRNA and protein levels were increased in breast cancer cells." (PMID 25605021, 2015). "Demographic, pathological and clinical variables were collected and correlations of TXNIP expression with clinicopathological factors of breast cancer patients were determined." (PMID 25605021, 2015). "We further evaluated TXNIP expression in response to anti-Her-2 treatment, to examine the role of TXNIP in the Her-1/2 pathway as well as its effects on OS of breast cancer patients." (PMID 25605021, 2015). "In clinical breast cancer tissues, we further demonstrate that miR-373 is positively associated with HIF1α and TWIST, and negatively associated with TXNIP." (PMID 26196741, 2015). "Here, we found a novel regulatory mechanism by which TXNIP expression is inhibited by microRNAs, such as miR-373, at the post-transcriptional level in metastatic breast cancers." (PMID 26196741, 2015). "Accordingly, a significant positive correlation was found between TXNIP and p27 using the breast cancer tissue-array (n=150) (r=0.340, P<0.001) that was confirmed in the external cohort (n=101) (r=0.331, P=0.001)." (PMID 25605021, 2015). "Collectively, our results suggest that dynamic regulation of TXNIP interaction with the Her-1/2 pathway contributes to OS of breast cancer." (PMID 25605021, 2015). "To better understand the interrelation of TXNRD1 and TXNIP with biologically relevant processes in breast cancer, we compared their expression levels with previously published metagenes." (PMID 20584310, 2010). "In order to understand the role of TXNRD1 and TXNIP for the natural history of breast cancer it seemed relevant to focus on untreated patients, because the thioredoxin system has been reported to influence sensitivity of tumor cells to chemotherapy." (PMID 20584310, 2010). "Breast cancers in the Miller dataset stratified based on TXNIP expression were found to have significant differences in clinical phenotypes; tumors with high TXNIP have better survival and clinical outcomes (p = 0.00115)." (PMID 20844768, 2010). "In the current study, we initially validated the results of the glucose-mediated expression of TXNIP obtained by the initial GEP screening by assessing the levels of mRNA by RT-PCR as compared to the level of TRX in breast cancer derived cell line MDA-MB-231." (PMID 17555594, 2007).
breast carcinoma (continued). "First, while the TXNIP-CAST interaction may have relevance in breast cancer, further studies are required to explore its broader relevance, tissue-specific regulation, and any role of post-translational modifications in the interaction." (PMID 40175348, 2025). "In addition, we identified a positive correlation between the expression of TXNIP and interleukin-24 (IL-24), a molecule that induces cancer-specific apoptosis in several breast cancer cell lines." (PMID 40175348, 2025). "Collectively, these findings unveil novel TXNIP-dependent pathways that may contribute to breast cancer pathogenesis, enriching our understanding of this molecule’s intricate role in cancer and potentially paving the way for clinical translation." (PMID 40175348, 2025). "In addition to identifying the novel interaction between CAST and TXNIP, our study revealed that overexpressing TXNIP increases IL-24 levels while knocking down TXNIP decreases IL-24 expression in breast cancer cells." (PMID 40175348, 2025). "Interestingly, breast cancer cell-derived exosomes negatively regulate TXNIP expression, resulting in the activation of the WNT/β-catenin pathway in fibroblasts and induction of cancer-associated fibroblasts (CAFs)." (PMID 37794178, 2023). "Further, there is a strong negative enrichment for transcripts correlated with TXNIP expression across breast cancers in the METABRIC database and Myc-associated gene signatures." (PMID 36930677, 2023). "Additionally, levels of thioredoxine interacting protein (TXNIP) decreased upon DASA-58 treatment in breast cancer cells." (PMID 35054968, 2022). "In human breast cancer, TXNIP has been shown to exhibit both prognostic and predictive value." (PMID 36366411, 2022). "Downregulation of TXNIP indicates a poor prognosis in breast cancers." (PMID 35450411, 2022). "Similarly, elevated TXNIP and a good prognosis of breast cancer and lung cancer were only correlated in the data sets of Kaplan–Meier-plotter and PrognoScan, but not of the GEPIA2." (PMID 35843949, 2022). "The expression of TXNIP in breast cancer tissues significantly decreases as the tumor progresses." (PMID 35450411, 2022). "The prognosis and predictive ability of TXNIP in human breast cancer have been confirmed." (PMID 35450411, 2022). "TXNIP’s prognostic and predictive abilities in human breast cancer cases have been confirmed." (PMID 36366411, 2022). "Another experiment shows that exosomes from breast cancer cells contain high levels of miRNA-146a, which reduces the expression of TXNIP to induce the Wnt/β-catenin axis, leading to activation of cancer-associated fibroblasts in the TME and promoting breast cancer progression." (PMID 35765040, 2022). "We have previously reported that the basal expression of TXNIP was markedly reduced in metastatic prostate and breast cancer cell lines compared to their benign counterparts, and that the overexpression of TXNIP inhibited the migration of androgen-independent PC3 prostate cancer cells." (PMID 36291127, 2022). "The expression of TXNIP in tumors is very low, and it may play an inhibitory role in many kinds of cancers such as liver cancer, breast cancer and lung cancer." (PMID 35280928, 2021). "Increasing evidence has shown that TXNIP expression is low in tumors and that it may act as a tumor suppressor in various cancer types such as hepatocarcinoma, breast cancer, and lung cancer." (PMID 33194655, 2020). "Chen and colleagues investigated the miR-373 could promote EMT and tumor invasion in breast cancer by suppressing the expression of thioredoxin-interacting protein (TXNIP)." (PMID 32411322, 2020). "It has been postulated that the activation of the miR-373-TXNIP-HIF1α-TWIST signaling axis is related to the poor prognosis of breast cancer patients and that TXNIP levels may be a potential prognostic biomarker for breast cancer." (PMID 33194655, 2020).